INS (insulin)
Diseases named in the same sentence as INS in open-access papers (continued):
Sharing a sentence is not in itself a finding about the gene and the disease.
Insulin resistance (continued). "Mice overexpressing glutathione peroxidase, Gpx1, developed insulin resistance associated with hyperinsulinemia, hyperglycemia, obesity and a 70% reduction in insulin-stimulated phosphorylation of insulin receptors, compared to wild type control mice." (PMID 23730255, 2012). "There are many genes candidates for GDM pathogenesis, including those associated with insulin secretion, insulin resistance, and obesity." (PMID 22927833, 2012). "It is recognized that IL-1β is one of the main cytokines implicated in the desensitization of insulin signaling and its genetic invalidation protects mice against diet-induced insulin resistance." (PMID 23316186, 2012). "It is also well established that T2D is caused by a combination of insulin resistance in skeletal muscle, liver, and adipose tissues and impaired insulin secretion from the pancreatic islets." (PMID 22973260, 2012). "Reports from diabetic animals and patients demonstrate that arginase activity is increased under diabetic conditions, while decreased insulin signaling is associated with diabetic insulin resistance." (PMID 22611498, 2012). "The association of IL-6 with insulin resistance was suggested by the observation in animal studies that passive immunoneutralisation of IL-6 led to an improved insulin sensitivity in insulin resistant mice with transgenic NFκB activation." (PMID 22615828, 2012). "The deterioration of the insulin-induced NO release is included between the major causes of endothelial dysfunction and cardiovascular disease related to obesity and insulin resistance." (PMID 22457831, 2012). "Previous studies from our laboratory and others have demonstrated that both fasting ATBF and the postprandial increase in ATBF are decreased in obese, insulin resistant subjects, which was closely associated with insulin resistance." (PMID 22768174, 2012). "In other words, (a) low insulin signaling are associated with good health and longevity and (b) insulin resistance is associated with poor health." (PMID 22683661, 2012). "Postoperative insulin resistance has been linked to nausea and vomiting, and to impairment of wellbeing but it can be limited or prevented by insulin, preoperative infusion, or oral administration of glucose." (PMID 22747890, 2012). "Insulin resistance is a metabolic disorder caused by the impairment of insulin function in inducing glucose uptake and utilization." (PMID 22287962, 2012). "Elevated 2-hour glucose is mainly related to peripheral insulin resistance and beta cell decompensation, whereas elevated fasting glucose is predominantly caused by hepatic insulin resistance and reduced first-phase insulin secretion." (PMID 22720085, 2012). "On the other hand, obesity and insulin resistance are also associated with increased lipid oxidation but result in impaired insulin action in the skeletal muscle." (PMID 23024761, 2012). "This muscle insulin resistance is caused by a free fatty acid-induced defect in insulin-stimulated glucose transport or phosphorylation, or both." (PMID 22363882, 2011). "Of interest these studies identified validated variants associated with insulin-secretory defects in the general population and showed little if any relationship to insulin resistance." (PMID 22208362, 2011). "Inactivation of CEACAM1 impairs insulin clearance and causes hyperinsulinemia, insulin resistance, dyslipidemia and visceral adiposity in transgenic mice." (PMID 21569294, 2011). "Two studies have also demonstrated modest evidence for association between SNPs in SORCS1 and fasting insulin, insulin sensitivity and insulin resistance in humans." (PMID 21294870, 2011). "These β-oxidation intermediates, such as acyl-CoAs or acyl-carnitines, have been linked to insulin resistance, although their potential impact on insulin signaling is unclear." (PMID 21589939, 2011). "On the contrary, others have reported that the T allele associated with elevated insulin/glucose values and insulin resistance." (PMID 21219602, 2011).
Insulin resistance (continued). "Obesity is usually associated with impaired glucose tolerance and insulin resistance, so we examined glucose tolerance and insulin sensitivity in the bitransgenic mice." (PMID 21738790, 2011). "Even without the development of manifest type 2 diabetes, chronically elevated insulin levels and insulin resistance are linked to a decreased lifespan and represent a better predictive marker for reduced longevity than glucose levels alone." (PMID 21070590, 2011). "Factors related to insulin resistance were significantly associated with quintiles of Cac: fasting insulin was positively and adiponectin negatively associated with Cac quintiles." (PMID 21533040, 2011). "Dietary trivalent Cr has been shown to play an important role in metabolic disorders associated with insulin resistance and hyperglycemia by providing significant beneficial effects in the insulin system." (PMID 21539728, 2011). "Gene variants related to insulin resistance such as insulin gene (VNTR), insulin receptor (INSR), insulin receptor substrate proteins (IRS1/2) and calpain-10 have shown to be associated with PCOS and related metabolic abnormality." (PMID 21492415, 2011). "The damage of insulin signal transduction causes insulin resistance, which is the main causation for the type 2 diabetes." (PMID 21305025, 2011). "The 16189 variant was also reported to be associated with higher fasting insulin and glucose levels, insulin resistance, and/or T2DM in Europe and Asia." (PMID 21298061, 2011). "Mechanistic studies have demonstrated that amylin can inhibit β cell insulin secretion, induce β cell apoptosis, and cause insulin resistance in both in vitro and in vivo systems." (PMID 21589925, 2011). "Our results were consistent with those of large-scale studies that found elevated serum calcium levels to be associated with insulin resistance, measured using fasting insulin or homeostatic model assessment." (PMID 21533040, 2011). "The discovery that miR-126 regulates insulin signaling provides novel insights into the molecular basis underlying mitochondrial dysfunction-derived pathogenesis of insulin resistance, and implicates miRNAs in metabolic diseases." (PMID 21464990, 2011). "Previous studies have confirmed that inhibition of insulin's vasoactive effect induces insulin resistance and hyperinsulinemia, which is the major cause of atherosclerosis and coronary artery spasm." (PMID 21801458, 2011). "These published variants were all associated with insulin-secretory defects in the general population and show little if any relationship to insulin resistance." (PMID 22208362, 2011). "Loss of hypothalamic insulin signaling is sufficient to induce obesity and peripheral insulin resistance." (PMID 22076142, 2011). "Diabetes mellitus is a chronic metabolic disease characterized by hyperglycemia, due to deficiency in insulin or insulin resistance, and represents a major cause of morbidity and mortality in contemporary societies." (PMID 25392740, 2011). "In a former study we demonstrated an association between anti-human PDI antibodies, fasting insulin and insulin resistance." (PMID 21949836, 2011). "Adipokines and cytokines, through their ability to interfere with insulin signaling, have been implicated in insulin resistance." (PMID 22144985, 2011). "Impaired insulin clearance can be the primary cause of insulin resistance by causing downregulation of insulin receptors and hepatic lipogenesis." (PMID 21569294, 2011). "First, it is well established that OSA is associated with insulin resistance and high insulin levels." (PMID 21943153, 2011). "The AR index was also more strongly correlated with the insulin resistance indexes and other risk factors including serum insulin, plasma glucose and whole blood HbA1C levels than adiponectin and resistin levels alone." (PMID 21251282, 2011).
Insulin resistance (continued). "Treatment of HIV-associated insulin resistance with a PPARγ agonist (rosiglitazone) significantly improved insulin sensitivity assessed with the hyperinsulinemic euglycemic clamp." (PMID 21559208, 2011). "Association of IL18 variation with insulin levels and estimates of insulin resistance were only observed in our adult study, suggesting that the effects of IL-18 are only associated with increasing age." (PMID 20227263, 2011). "Insulin resistance in skeletal muscle is considered especially pathogenic, as this tissue accounts for the majority of insulin-stimulated glucose disposal." (PMID 22194858, 2011). "Conversely, resistin has been implicated in impairing insulin sensitivity in rodents, while its role in the development of insulin resistance in humans is still controversial." (PMID 21760816, 2011). "The mechanisms responsible for inducing resistance to insulin are not completely understood, but accumulating data point to a robust association between insulin resistance and inflammation." (PMID 21738773, 2011). "The commonly accepted model attributes the development of type 2 diabetes (T2D) to relative insulin deficiency, which results from peripheral insulin resistance, and reduced insulin release due to defective insulin secretion and diminished beta cell mass." (PMID 22046328, 2011). "A reduction in adiponectin expression has been associated with insulin resistance, whereas administration of adiponectin is accompanied by an increase in insulin sensitivity." (PMID 21760816, 2011). "The 5227GG genotype was associated with serum levels of insulin (P = .006) and homeostasis model assessment of insulin resistance (P = .007)." (PMID 20619427, 2011). "A similar inconsistency has been reported for muscle, where mRNA levels are positively associated with insulin sensitivity or with insulin resistance." (PMID 21284833, 2011). "Subsequently, experimentally induced brain insulin resistance models have shown that altered insulin signalling causes cognitive deficits and, at least in some instances influences aspects of AD pathology." (PMID 21347323, 2011). "Given that insulin resistance and obesity appear intrinsically linked, we performed further analyses to consider the role of insulin in the identified associations and interactions." (PMID 22069463, 2011). "Unexpectedly, an inverse, marginally significant association between insulin resistance and cancer recurrence was observed in the ER/PR-positive group; this trend was also observed in the analyses of serum insulin levels." (PMID 21450081, 2011). "Type 2 diabetes mellitus is a metabolic disease characterized by chronic hyperglycemia which mainly results from a deficiency in peripheral insulin effects (insulin resistance)." (PMID 21699724, 2011). "The C-allele in rs2877716 (ADCY5) was nominally associated with parameters of insulin secretion and insulin resistance, such as a lower fasting plasma insulin, peak insulin, HOMA-B and a higher QUICKI and ISI, but showed no impact on blood glucose parameters." (PMID 21789219, 2011). "Visceral obesity, high insulin levels and insulin resistance have been associated with increased risk of OSA." (PMID 21943153, 2011). "Accordingly, weight loss (thus reduction of adipose tissue) will reduce insulin levels and insulin resistance." (PMID 22035351, 2011). "Epidemiologic studies have shown that higher serum levels of insulin and insulin resistance are associated with an increased risk of PC, even after adjustment for BMI, body fat, levels of sex hormone, and insulin-like growth factor 1 (IGF-1)." (PMID 22110984, 2011). "The widely recognized association between NAFLD and insulin resistance suggests a role of the insulin signaling pathway in hepatic steatosis." (PMID 21479224, 2011). "An alteration in any of the related pathways reduces insulin's effectiveness and leads to the insulin-resistance and glucose intolerance associated with advancing age." (PMID 21733182, 2011).
Insulin resistance (continued). "Oxidative stress induced by the accumulation of reactive oxygen species (ROS) has a causal role in the development of insulin resistance, whereas ROS themselves function as intracellular second messengers that promote insulin signal transduction." (PMID 22102892, 2011). "Insulin resistance in Zucker fatty or diabetic fatty rats has been associated with higher basal insulin secretion caused by increased fuel metabolism in pancreatic beta cells." (PMID 21731709, 2011). "FFAs cause insulin resistance in all major insulin target organs (skeletal muscle, liver, and endothelial cells) and have emerged as a major link between obesity, the development of the metabolic syndrome, and atherosclerotic vascular disease." (PMID 21754922, 2011). "The presence of hypertriglyceridemia, low HDL-C concentrations, and high TG/HDL-C ratios almost never occurred as isolated disorders, and were nearly always associated with insulin resistance because insulin affects TG and HDL-C metabolism." (PMID 21586120, 2011). "This process has been linked to a downregulation of insulin cell signaling, resulting in insulin resistance." (PMID 21437191, 2011). "In conclusion, the association of genetic variation within IL18 on insulin levels and estimates of insulin resistance were only observed in our older GrOW study, suggesting that the effects of IL-18 appear to be more prominent as we age." (PMID 20227263, 2011). "For example, monogenic diseases with impaired sensing of glucose, lowered insulin secretion or increased insulin resistance are associated with impaired fetal growth." (PMID 21771322, 2011). "Insulin resistance is associated with increased levels of serum insulin and depletion of β-cells and results in impaired regulation of circulating lipoprotein and glucose levels." (PMID 21172030, 2010). "Low plasma ghrelin levels are associated with elevated fasting insulin levels and insulin resistance, suggesting both physiological and pathophysiological roles for ghrelin." (PMID 20700401, 2010). "In type 2 diabetes also, the inflammation leading to the activation of monocytes is postulated to be important for enhancing insulin resistance and contributing to the loss of insulin secretary function by islet cells." (PMID 20868496, 2010). "Second, insulin resistance has been associated with a reduction in the phosphorylation (activity) of insulin signaling molecules." (PMID 21187969, 2010). "Previous studies reported associations of rs9939609 with fasting glucose, fasting insulin, or insulin resistance." (PMID 20377915, 2010). "A variety of metabolic diseases are highly associated with insulin resistance, as defined by the desensitization of target cells to insulin." (PMID 20814441, 2010). "This association of serum RBP4 to endogenous insulin secretion and insulin resistance was in sharp contrast to other adipocytokines." (PMID 20932285, 2010). "• Influence on insulin resistance(IR) and serum insulin: JQJT tablets can improve the insulin resistance caused by Hydrocortisone and decrease the serum insulin in mice." (PMID 20214831, 2010). "Cell differentiation has also been implicated in insulin resistance in the sense that insulin resistant adipose tissue displayed lower expression of differentiation markers than their insulin sensitive counterparts." (PMID 20361040, 2010). "The presence of decreased GH secretion is associated with increased serum insulin levels and insulin resistance indices." (PMID 20150954, 2010). "This latter observation is in conflict with previous reports that shortened telomeres in humans are associated with insulin resistance, a state in which insulin sensitivity is reduced." (PMID 20876939, 2010). "Gastric bypass causes rapid resolution of insulin resistance and improved insulin secretion, perhaps mediated in part by increased GLP-1, even before major weight loss has been achieved." (PMID 20470376, 2010).
Insulin resistance (continued). "In the pancreas, estrogen receptors (ERs) are important in the regulation of insulin biosynthesis and release, a process that appears to counteract the increased insulin resistance associated with pregnancy." (PMID 20488778, 2010). "The observed data are consistent with the observation that depression is frequently linked with insulin resistance: reduced glucose utilization and elevated insulin secretion following glucose administration have been shown in depressed patients." (PMID 20161799, 2010). "To determine the role of insulin action in macrophages and monocytes in obesity-associated insulin resistance, we conditionally inactivated the insulin receptor (IR) gene in myeloid lineage cells in mice (IRΔmyel-mice)." (PMID 20463885, 2010). "Diabetes mellitus a lifelong progressive disease is a chronic metabolic disorder due to the relative deficiency of insulin secretion and varying degrees of insulin resistance and is characterized by high circulating glucose." (PMID 20630072, 2010). "Cross-sectional data provide some evidence that circulating 25-hydroxyvitamin D (25(OH)D) is inversely associated with insulin resistance, although direct measurements of insulin sensitivity are required for confirmation." (PMID 20011094, 2010). "These and other proteins (i.e. ASP, MPO, PAI-1 and VEGF) included in this cluster and in cluster 1 that was associated with insulin were previously found to be increased in subjects with insulin resistance, CVD, or both." (PMID 21203453, 2010). "The management of diabetic conditions by insulin therapy has several drawbacks like insulin resistance and in chronic treatment causes anaeroxia nervosa, brain atrophy and fatty liver." (PMID 20630072, 2010). "We first proposed that insulin resistance (IR) is linked to iNOS induction in skeletal muscle and other insulin target cells during systemic inflammation." (PMID 21206533, 2010). "Overproduction of hepatic VLDL that results from the loss of insulin responsiveness is often seen in insulin resistance conditions, which is associated with increased posttranslational stability of apoB-100." (PMID 20423497, 2010). "Insulin resistance (IR), a reduced physiological response of peripheral tissues to the action of insulin, is one of the major causes of type 2 diabetes." (PMID 20482756, 2010). "Skeletal muscle is the major site of insulin mediated glucose disposal (Rd) and muscular insulin resistance is a major risk factor for type 2 diabetes (T2D) in PCOS." (PMID 21209881, 2010). "Insulin resistance (IR), a reduced physiological response of peripheral tissues to the action of insulin, is one of the major causes of type 2 diabetes and plays a critical role in the pathogenesis of cardiovascular diseases (CVDs)." (PMID 20482756, 2010). "Overproduction of cortisol is reportedly associated with insulin resistance, and higher cortisol concentrations are also related to reduced insulin secretion." (PMID 21171971, 2010). "Hypertriglyceridemia and low HDL-C almost never occurred as isolated disorders, and were nearly always associated with insulin resistance because insulin affects very low-density lipoprotein and HDL-C metabolism." (PMID 21134293, 2010). "Treatment with atRA restored this change, induced weight loss, and improved insulin responsiveness, suggesting that suppression of obesity and insulin resistance by atRA is largely mediated by PPARβ/δ." (PMID 20559430, 2010). "Clinically, the association between insulin resistance and pre-hypertension has been demonstrated, and it has also been proposed that insulin promotes renal sodium retention (and references therein)." (PMID 20886000, 2010). "Exposure of human skeletal muscle cells to MCP-1 at physiologic concentrations has been demonstrated to induce a state of increased insulin resistance, as indicated by alterations in insulin signaling with an associated impairment of glucose uptake." (PMID 20950459, 2010).